ALB (albumin)
Diseases named in the same sentence as ALB in open-access papers (continued):
Sharing a sentence is not in itself a finding about the gene and the disease.
tumor (continued). "On the other hand, tumor-induced rat group treated with Zn-NPs showed a significant increase in both plasma albumin and total proteins concentrations upon its comparison with Fe-NTA model." (PMID 35083709, 2023). "And it was shown that upregulation of albumin promotes tumor proliferation and metastasis via activating expression of tumor necrosis factor-α, interleukin-1, and interleukin-6." (PMID 37251954, 2023). "Compared to Taxol®, the albumin carrier improves drug delivery from the bloodstream to the tumor site and allows for larger drug doses." (PMID 36770535, 2023). "One strategy has been to attach an albumin-binder to extend circulation and increase tumor accumulation, with apparently encouraging results." (PMID 37376181, 2023). "As expected, the albumin-binder-conjugated [177Lu]Lu-HTK03170 delivered a higher radiation dose (6.7-fold) to tumor than its non-albumin-binder-conjugated analog [177Lu]Lu-HTK03149." (PMID 37649602, 2023). "The decrease in albumin levels is more pronounced in the middle and late stages of tumor patients, leading to hypoalbuminemia." (PMID 37853186, 2023). "Herein, we used a lipophilic NIR-II fluorescence molecule, BPBBT, as a model drug to investigate the tumor entrance of the albumin-bound nanoparticles." (PMID 36839841, 2023). "DTX-NPs constructed by using human serum albumin (HSA) demonstrated that these NPs can offer promising anti-tumor activity with low systemic toxicity." (PMID 37909596, 2023). "Univariate Cox regression analysis showed that age, gender, Child-Pugh, BCLC stage, tumor size, tumor number, lymphocyte count, TBIL, DBIL, GGT, ALP, albumin, INR, and PT were associated with RFS." (PMID 37700838, 2023). "As part of the validation, we revealed that the albumin and doxorubicin conjugate (HSA‐TC‐proDOX) exhibited good tumor targeting in vivo and enhanced cancer cellular uptake in vitro." (PMID 36684090, 2023). "GIs can efficiently assemble with endogenous albumin to form GIAs and self-deliver to the tumor region." (PMID 37593108, 2023). "The efficiency of albumin-based delivery systems is determined by their ability to improve tumor targeting and accumulation." (PMID 37836018, 2023). "Secondly, variables such as age, tumor size, leucocyte, albumin, and lymphocytes/monocytes have been identified as independent predictors of LNM in pancreatic head cancer." (PMID 37442865, 2023). "The octogenarian group had a significant association with lower BMI (p = 0.042), lower albumin (p = 0.019), a higher ASA score (p < 0.001), and an earlier tumor stage (p = 0.023)." (PMID 38068325, 2023). "The risk factors for RFS in tumours smaller than 5 cm included male sex, increased AST levels, low albumin levels, and multiple tumours." (PMID 35268459, 2022). "The ORs (95%CIs) of upper 3rd tertile albumin-corrected Ca and upper 3rd tertile of tumor size was 4.78(1.39, 16.38) and 4.07(1.12,14.84) for participants with adult famine exposure, respectively." (PMID 35784571, 2022). "Albumin nanoparticles can accumulate in the tumor site, and macrophage membranes can reduce the clearance of albumin by RES and enhance the target capacity to tumor." (PMID 36575429, 2022). "The 10 most important features in the stacking model were the primary tumor site, tumor volume, age at diagnosis, histological tumor grade, tumor type, and preoperative HB level, albumin level, platelet count, NLR, and eosinophil ratio." (PMID 36620593, 2022). "Six proteins (LMNA, LCP1, HSPD1, CS, CA1, and ALB) were previously identified as differentially expressed between the tumor center and margin." (PMID 35512017, 2022). "Tumor burden score (TBS) is a continuous variable to measure the extent of tumor involvement, and the albumin–bilirubin (ALBI) grade is an objective model to estimate hepatic functional reserve." (PMID 35158917, 2022).
tumor (continued). "To directly determine if SOX8 alters albumin uptake in tumor cell lines, we added Nab-p to control, SOX8 overexpression and SOX8 knockdown cells and performed immunoblotting with a human specific primary antibody to albumin." (PMID 35173526, 2022). "By examining 1714 patients across 16 cancer types, we found that high pretreatment serum albumin level predicts favorable tumor radiographic response following ICB treatment in a dose-dependent fashion." (PMID 35393553, 2022). "In a study of a physical examination crowd, the correlation between low levels of ALB and tumor morbidity and mortality was also found." (PMID 36290873, 2022). "This work is a good example of the very useful properties of albumin to cover NPs to increase their stability, biocompatibility, tumor accumulation and clearance." (PMID 36230578, 2022). "Patients with cancer reportedly exhibit a stereotypical acute-phase protein response with CRP increasing and albumin falling, which is maintained across different tumor types." (PMID 35807934, 2022). "The tumor homing peptide LyP-1 was conjugated to abraxane, a clinically approved paclitaxel-albumin nanoparticle, then administered to mice bearing human cancer xenografts." (PMID 35744930, 2022). "The microenvironmental anti-inflammatory properties of bromelain by uncoated cancer cells (depolymerizing MUC-1, fibrin and albumin) through increasing adhesion of lymphocytes to the tumor are thought to expose the tumor to host defense." (PMID 36506883, 2022). "Human serum albumin has risen as a great carrier for therapeutic agents, improving their pharmacokinetic profiles or delivering them to the tumor sites." (PMID 35203695, 2022). "One of the important reasons for using albumin as an anti-tumor drug carrier is that albumin-binding proteins such as gp60 and SPARC are abundantly expressed in tumor cells." (PMID 36359230, 2022). "Decreased albumin levels indicate the poor nutritional status of the patient or the consumption of the tumor." (PMID 36439900, 2022). "We believe DOX is easily delivered to tumor cells due to the conjugation of anti-vascular endothelial growth factor (VEGF) antibodies with bovine serum albumin-coated PEGylated magnetic NPs." (PMID 35877371, 2022). "In recent years, there have been several studies on using routine blood parameters as potential tumor prognostic markers, including C-reactive protein, albumin, neutrophil count, lymphocyte count and other leukocyte count." (PMID 34980025, 2022). "Results indicated that albumin is a premier molecule for the impressive delivery of 99mTc-resveratrol at tumor locations in comparison with gold nanoparticles." (PMID 36552412, 2022). "A univariate Cox hazard regression analyses identified a high splenic volume-to-BSA ratio, low albumin, high bilirubin, and a large tumor size as significant prognostic factor." (PMID 35394184, 2022). "No statistical differences between the groups according to sex, neutrophil/lymphocyte ratio, albumin/globulin ratio, site of tumour, Lauren and OMS’ classification, perineural invasion, differentiation and tumour stage (pT) were observed." (PMID 35919233, 2022). "It has been reported that IL-6 secreted by tumor-related fibroblasts can inhibit pre-albumin and stimulate fibrinogen, resulting in the decrease of pre-albumin and the increase of fibrinogen." (PMID 35033080, 2022). "CRP and albumin-to-globulin ratio (AGR) significantly correlated with maximal tumor dimension and thiol group levels." (PMID 35629255, 2022).
tumor (continued). "Among these 9 candidate targets, AGT, DRD2, IL-1B, and IL-6 were significantly increased in primary tumor compared with the normal tissues, while ALB, IL-10, and IGF1 were significantly decreased in COAD tissues." (PMID 35280511, 2022). "It is also noteworthy that there were so few changes in DGE between primary and paired CRLM tumours, and discrimination between groups in sPLS‐DA was predominantly due to albumin overexpression in the liver samples, possibly as a contaminant." (PMID 34874125, 2022). "Its tumor uptake was enhanced not only by the tumor targeting capacity of 3PRGD2 but also by the albumin carrier characteristics of palmitic acid." (PMID 35890224, 2022). "After its passive accumulation in tumor tissues, albumin is captured by overexpressed receptors and selectively endocytosed to cancer cells." (PMID 35456562, 2022). "The most commonly used predictors for developing prognostic models were AFP, albumin, bilirubin, Child–Pugh class, liver metastasis, tumor size, and vascular invasion." (PMID 35810271, 2022). "The linkage of Albumin to IFNβ not only extends half-life and but also leads to the targeting of IFNβ to the LNs and tumor in vivo and thereby serves as a potent adjuvant for vaccination." (PMID 35459734, 2022). "Tumor cells from P09 and P10 were selected for this analysis as they contained a comparable number of ALB + and ID3 + cells." (PMID 35347134, 2022). "In the present study, we determined the effects of pretreatment albumin on both radiographic tumor response and survival of patients across 16 different cancer types." (PMID 35393553, 2022). "Despite advances in new methodologies, routine measurement of specific tumour markers remains challenging because some of them are rapidly degraded, difficult to assay and/or masked by highly abundant blood proteins like ALB, AAT, or HP." (PMID 35174082, 2022). "It is known that serum albumin accumulates in regions of proliferating tumor cells, which is thought to be a result of the enhanced permeability and retention effect (EPR)." (PMID 35164144, 2022). "They utilized a water-soluble phthalocyanine derivative (PcN4) that bound to endogenous albumin dimers to become complexes with tumor-targeting properties and improved the activity of PDT." (PMID 36015206, 2022). "Based on univariate logistic regression, Age > 60 (P = 0.038), tumor-bearing status (P = 0.002), albumin < 3.5 (P = 0.004), Child–Pugh B (P < 0.001) and MMP1 (P < 0.001) were significantly correlated with OS." (PMID 35948625, 2022). "First, in vitro analysis confirmed that reassembling of abPTX formed uniform and stable serum albumin nanoparticles (NP-abPTX) with size of 107.5 ± 2.29 nm and reserved the ability to kill tumor cells." (PMID 35244505, 2022). "Caveolae transports the albumin–paclitaxel conjugate to the extracellular space, including the tumor stroma." (PMID 35740909, 2022). "There, SPARC (secreted protein, acidic and rich in cysteine) that is selectively secreted by the tumors binds to albumin-bound paclitaxel with the resulting release of paclitaxel in the vicinity of tumor cells." (PMID 35740909, 2022). "Tumor mice were divided into five groups receiving cyclophosphamide, albumin, PBS, free artemether and encapsulated artemether." (PMID 36359230, 2022). "The albumin-prodrug conjugate inhibits tumor metastasis by inducing cytotoxicity preferentially on tumor cells after efficiently draining into lymph nodes." (PMID 35317221, 2022). "We performed multivariable analyses taking into account age, sex, race, distant metastasis, tumor location, SUVmax, total bilirubin, CA 19-9, albumin, surgery, chemoradiation, and chemotherapy." (PMID 36475189, 2022). "Xu, Ren, and co-workers reported albumin/sulfonamide-stabilized iron porphyrin metal-organic framework nanocomposites that target tumor hypoxia through accumulation in tumors overexpressing carbonic anhydrase IX." (PMID 35884281, 2022).
tumor (continued). "Denatured albumin nanoparticles prepared via desolvation method can be specifically internalized by activated neutrophils in vivo and delivered to inflammation or tumor tissues." (PMID 35244505, 2022). "The micelle-bearing albumin crossed the tumor vascular endothelium through gp60-mediated transcytosis and did bind to cysteine in the stroma accumulating at the tumor site." (PMID 36612002, 2022). "As compared with its precursor, aldoxorubicin is covalently attached to albumin in circulation and shows mitigated cardiac toxicity attributed to purposive tumor targeting." (PMID 36499357, 2022). "Patients with a high Ki-67 expression had higher albumin levels, larger tumor size, higher T1rt-pre, higher T1rt-20min, and lower ADC (all P < 0.05)." (PMID 36313692, 2022). "ALB, BW, specific tumor type, sex, and PS should be considered for the future development of the PPK model of anti-PD-1 mAbs." (PMID 35983041, 2022). "Several studies have demonstrated the expression of ALB in iCCA, but the features of these ALB + tumor cells are still unclear." (PMID 35347134, 2022). "It is known that tumor cells ingest more albumin into their lysosomal compartments than normal cells, and albumin has a natural ability to accumulate at some disease sites." (PMID 36559265, 2022). "In order of significance, the tumor number, serum albumin level, and des-gamma-carboxyprothrombin level were the most important variables for the prediction of HCC recurrence in the GBDT model." (PMID 39129938, 2022). "Biotin (biotin-specific receptor), trastuzumab (HER2 targeting antibody) and CREKA (tumor homing peptide) have also been assessed to provide albumin nanoparticles with additional active targeting of tumors." (PMID 35456562, 2022). "Like many other nanoparticle carriers, albumin nanoparticles are 50–200 nm in diameter, facilitating extravasation into tumor tissue via the EPR effect, and they can be functionalized for targeted delivery." (PMID 36365214, 2022). "BMI and serum ALB are not only represent the nutritional status of patients to some extent, but also closely related to tumor progression." (PMID 35948974, 2022). "Its accumulation in solid tumors via the EPR effect is the rationale behind developing albumin-based drug delivery systems for tumor targeting." (PMID 36678688, 2022). "Then, albumin nanoparticles enter the tumor interstitium and bind to SPARC proteins, releasing the entrapped drug." (PMID 35267507, 2022). "Another study compared the potential of gold nanoparticles loaded 99mTc-resveratrol with albumin loaded 99mTc-resveratrol for tumor special delivery." (PMID 36552412, 2022). "Albumin accumulates in certain tumor cells via macropinocytosis, so albumin-coupled cytotoxic drugs can be designed to carry anticancer agents." (PMID 36046825, 2022). "Comparison between groups found that a low PNI was associated with lower BMI, lymphocyte count, albumin, and hemoglobin concentrations, higher ASA score, more advanced tumor stage, higher frequency of blood transfusion, but less frequency of PAC." (PMID 35354923, 2022). "The risk factors for OS in tumours smaller than 5 cm included increased aspartate aminotransferase (AST) (log-transformed) and low albumin levels, multiple tumours, and high Edmondson–Steiner grades." (PMID 35268459, 2022). "The levels of ALB, crCa, tumor size, tumor volume, and postoperative PTH demonstrated statistically significant differences between stages." (PMID 35663321, 2022). "As a standard, LDH, CRP, albumin, hemoglobin and platelets (all components of the LabBM score) must be available and in addition, the added value of a given tumor marker is studied in a multivariable model." (PMID 36531068, 2022). "Laboratory indicators such as red blood cells, hemoglobin, lymphocyte percentage, C-reactive protein, ferritin, albumin, and γ-glutamyl transpeptidase levels are also correlated with the tumor burden." (PMID 35013456, 2022).
tumor (continued). "We investigated numerous clinical features, including tumor status, demographic information, and laboratory tests (e.g., creatinine, estimated glomerular filtration rate, albumin, hemoglobin, and C-reactive protein)." (PMID 35804319, 2022). "Taken together, albumin is an effective carrier for the specific delivery of drug molecules to tumor sites." (PMID 35416106, 2022). "Based on the distinct improvement in paclitaxel tumor therapy, as well as the similarities in treatment challenges between paclitaxel and MT, we developed an albumin-stabilized MT formulation (BSA-MT)." (PMID 36145639, 2022). "In the presence of tumor antigen, IL-12-loaded human serum albumin (HSA) nanoparticles are released from INS-CAR T, allowing for local and controlled IL-12 release (and recruitment of other CAR-T cells)." (PMID 36248810, 2022). "A slight increase in albumin shows maintained stability, and in the albumin-enriched environment, the signal is activated at the tumour area as two monomers." (PMID 35865904, 2022). "Stability, circulation time, and tumor uptake of peptides can also be increased by chemical ligation ex vivo to serum albumin (taking advantage of albumin’s size, long circulation time, and renal recycling)." (PMID 35456579, 2022). "In vivo study showed that tumor shrink was most significant in albumin-bound paclitaxel combined with UNC1999 group compared with the other three groups." (PMID 35173526, 2022). "A rise in the concentration of CSF tumor makers more than 2–3% of serum values is unlikely due to simple diffusion or serum contamination unless an increased CSF albumin concentration is also present- which indicates disruption of the BBB." (PMID 36612116, 2022). "Once administered, the PFTBA:albumin nanoparticles take advantage of the EPR effect to passively accumulate at the tumor and release the bound O2." (PMID 35057001, 2022). "Biochemical parameters of liver function (AST, ALT, GGT, total protein, albumin), tumor volume, oxidative stress [malondialdehyde, (MDA)] and antioxidative [superoxide dismutase (SOD), and reduced glutathione (GSH)] markers were measured." (PMID 35444229, 2022). "PERTINENT FINDINGS: Albumin binder–conjugated FAPI radiopharmaceuticals exhibited notably improved tumor uptake and retention compared with the original FAPI tracers and showed remarkable inhibition of PDX tumor growth, with negligible side effects." (PMID 34593598, 2022). "Trp availability to tissues and tumours is determined in part by extent of binding of the amino acid to plasma albumin, which is controlled by circulating [albumin] and [NEFA]." (PMID 36286592, 2022). "The study showed that vascular invasion, albumin, tumor size, log10 bilirubin, tumor number, age, and sex were significant prognostic variables." (PMID 35625962, 2022). "Taking advantage of the interactions between platelets and tumor cells, two schemes, direct and indirect, were proposed to target the modified human serum albumin submicron particles (HSA-MPs) towards tumor cells." (PMID 36430755, 2022). "In models 2 and 4, the variables age, sex, NLR, PLR, albumin levels, bilirubin levels, maximum tumor size, TACE session, and ECOG PS were adjusted." (PMID 36618073, 2022). "Nab-paclitaxel is an innovative molecule which depletes tumor stroma through interaction between albumin and secreted acidic protein which is rich in cysteine." (PMID 35646689, 2022). "The included studies were heterogeneous regarding tumor type, sample size, and albumin cut-offs, although we conducted subgroup analyses for these factors and observed consistent results." (PMID 36533070, 2022). "Tumors secrete cysteine-rich acidic proteins such as SPARC during growth that attract adherent albumin, thereby allowing drug translocation from the tissue interstitium into the tumor cells, eventually increasing the intra-tumoral accumulation of albumin NPs." (PMID 35366890, 2022).